EGFR (epidermal growth factor receptor)
Diseases named in the same sentence as EGFR in open-access papers (continued):
Sharing a sentence is not in itself a finding about the gene and the disease.
tumor (continued). "MYL1 promoted HSCC metastasis and correlated with tumor immune infiltration in HNSCC, these functions may be related to the EGF/EGFR signaling pathway." (PMID 37679666, 2023). "Compared to non‐tumour tissues, the mRNAs in LUAD were also enriched in EGFR signalling pathway." (PMID 36650118, 2023). "The CAF-secreted urokinase-type plasminogen activator (uPA) binds to its receptor (uPAR), activating the integrin and epidermal growth factor receptor (EGFR) pathways and resulting in the subsequent activation of ERK and reduction of p38 activity, which promotes tumor cell proliferation." (PMID 37173977, 2023). "In addition, EGFR overexpression is a common feature of GBM, promoting invasion and aggressiveness of tumor cells." (PMID 37122703, 2023). "In the front-line setting, C797S occur in 7% of patients and has been shown to emerge in the absence of T790M, in which case the tumor remain sensitive to first generation EGFR-TKIs." (PMID 36672453, 2023). "In order to elucidate the molecular mechanism of action of ZR2002 in the tumor, we analyzed the effects of its two main components, i.e., the 2-chloroethyl DNA-damaging moiety with P-H2AX and the quinazoline-based scaffold as an EGFR inhibitor." (PMID 36980255, 2023). "Indeed, rare MET amplified cell subpopulations, representing <1% of cells in a tumor, have reportedly been uncovered in treatment-naïve cases of EGFRm+ NSCLC that subsequently progressed on EGFR-TKIs with MET amplification as the main mechanism of resistance." (PMID 37685884, 2023). "The non-canonical nuclear localization and function of EGFR have been studied extensively, and greater clarity is emerging about their impact on tumor development." (PMID 36977662, 2023). "Consequently, in the context of this work, the downregulation of RAB27A leads to a reduction in EGFR membrane expression within OSCC cells, thereby diminishing traits driven by the EGFR, such as tumor growth and resistance to apoptosis." (PMID 37685910, 2023). "In addition, smoking affects the effect of chemotherapy in advanced patients, and a significant difference in tumor biology is the higher EGFR mutation rate of never smokers, which may explain the better prognosis of never smokers after treatment for the EGFR gene." (PMID 36994380, 2023). "Moreover, NRP1 can activate EGFR phosphorylation, subsequently activating the downstream AKT-mTOR pathway, and ultimately contributing to tumor progression in PCa." (PMID 36841806, 2023). "This open-label, phase 1 study provided novel findings regarding the safety and tumor response of DS-1205c, a kinase inhibitor that selectively targets AXL, in combination with osimertinib in 13 patients with metastatic or unresectable EGFR-mutant NSCLC." (PMID 36892745, 2023). "Since the size of the tumor in the early acquired resistance period does not increase, the early acquired resistance to EGFR-TKIs before radiographic advance can hardly be perceived by the naked eye of clinicians." (PMID 37730961, 2023). "Accordingly, rather than EGFR protein levels, phosphorylated receptor levels should represent a better biomarker for EGFR pathway activation in tumor samples." (PMID 36817764, 2023). "High-throughput pharmacological screens of ten EGFR-driven GBM samples identified the combination of erlotinib (EGFRi) and MLN0128 (a mammalian target of rapamycin inhibitor, or MTORi) as the most effective at inhibiting tumor cell viability." (PMID 36831214, 2023). "As PVRAP interacts with PVR, we propose that PVRAP could act as a tumor suppressor by regulating PVR activity, similar to the relationship between EGFRAP and EGFR." (PMID 37510408, 2023).
tumor (continued). "EGFR-amplified tumours tended to be primarily classical in both primary (16/20) and recurrence (16/19), and EGFR non-amplified tumours tended to be classical (14/21) and mesenchymal (7/21) in recurrence." (PMID 36765632, 2023). "Moreover, the tumor-stroma interaction was associated with higher activation of the hepatocyte growth factor/MET-mediated PI3K/AKT signaling pathway and epithelial-mesenchymal transition process, supporting the hypothesis of fibroblast-involved resistance to EGFR TKI treatment." (PMID 36647832, 2023). "It blocks the epidermal growth factor receptor (EGFR), leading to tumour growth inhibition." (PMID 36820891, 2023). "Based on the data presented here, CD27xEGFR may provide tumor-localized binding and crosslinking of CD27 on T cells for EGFR+ carcinomas." (PMID 37545491, 2023). "In P129, 3D reconstruction of the CE and NE tumor segments, using T1 + C and T2W/FLAIR, respectively, showed the distribution of MRI-localized biopsy samples and exposed the molecular heterogeneity of EGFR at different sites." (PMID 37770427, 2023). "Therefore, the combination of clinically in-use kinase inhibitors (e.g., against the EGFR, BRAF or MEK1/2) with NHR ligands is a promising avenue for dual targeting of oncogenic signaling in tumor cells and simultaneous empowerment of host immunity." (PMID 37686465, 2023). "Tumor associated macrophages (TAMs) which are broadly considered M2-like secrete a large number of cytokines including PGE2, epithelial growth factor (EGF), epithelial growth ligands of the factor receptor (EGFR), IL-10 and TGF-β, which stimulate tumor cell proliferation and survival." (PMID 37064113, 2023). "More particularly, genetic modification (glycosylation) of PD-L1 that is induced by cancer cells via EGFR/B3GNT3 axis suppresses this tumor-suppressive effect of autophagy-mediated PD-L1 degradation, promoting tumor growth and evasion of immune surveillance mechanism in breast cancer models." (PMID 36833401, 2023). "Among mechanisms of therapy resistance to EGFR inhibitors are: PTEN (phosphatase and tensin homolog) alterations, deregulated PI3K (phosphatidylinositol 3-kinase) pathway, compensatory signaling pathways, tumor heterogeneity and ineffective BBB penetration." (PMID 36900355, 2023). "To investigate the potential role of EGFR in limiting trametinib efficacy, we reduced the expression of EGFR by shRNA in the CAL33 and HSC3 cell lines and then evaluated the sensitivity of tumor cells to trametinib in vitro and in vivo." (PMID 37501404, 2023). "Our data indicate that these novel peptides are highly specific ligands for the EGFR overexpressed in TNBC cells, and thus they could be used in conjugation with nanoparticles for tumor-targeted delivery of anticancer drugs." (PMID 37048151, 2023). "Similarly, the binding of Wnt ligands to activated EGFR induces β-catenin/TCF/LEF to form a complex with the PD-L1 promoter region and induces PD-L1 mRNA expression in tumor cells." (PMID 38299148, 2023). "In this trial, pretreatment EGFR tumor marker (protein) expression, but not EGFR mRNA expression, was a prognostic marker in TN-IBC." (PMID 37048158, 2023). "Thus, in a model of EGFR-driven epithelial neoplasia in Drosophila, lactate dehydrogenase (LDH) was upregulated and required for the transition from hyperplasia to neoplasia." (PMID 37190033, 2023). "For LUAD, TKI targeting EGFR, such as Gefitinib, promotes G2/M phase arrest to inhibit tumor growth but fails to do so in TKI resistant cells." (PMID 36959566, 2023). "Similarly, FYLM synergizes with osimertinib to reduce the protein levels of p-EGFR and p-Akt in LLC triple-mutant tumor-bearing mice." (PMID 36744262, 2023). "We conclude that when training patch-based models, tumor regions contain the highest signal for EGFR classification and that excluding non-tumor regions from consideration reduces noise and increases performance." (PMID 36927889, 2023).
tumor (continued). "Additional preclinical research has shown that EGFR blockade may inhibit telomerase activity in CSCC and thus suppress tumor cell survival." (PMID 37417890, 2023). "The present review explores the potential of targeted epidermal growth factor receptor (EGFR) nanotherapy as an alternative treatment for NSCLC, showing that EGFR-targeted nanoparticles are efficiently taken up by NSCLC cells, leading to a significant reduction in tumor growth in mouse models." (PMID 37754880, 2023). "While mAbs efficiently target cell surface receptors, such as EGFR, their tumor cell internalization is limited and often does not lead to significant boron localization in key organelles, including the cell mitochondria and nuclei." (PMID 37444386, 2023). "Notably, TRPV1 inhibition by AMG9810 robustly dampened EGFR or AKT phosphorylation and downregulated MCL1 expression in the tumor cells." (PMID 37165076, 2023). "In conclusion, our study provides, for the first time, absolute quantification of RTKs in liver tissue from healthy individuals and cancer patients with a focus on CRLM, reflecting a significant suppression of EGFR, INSR, VGFR3, and AXL, and upregulation of IGF1R, EPHA2 and PGFRB in tumour." (PMID 36890818, 2023). "John Mendelsohn noted that the addition of EGF, the ligand of the EGFR receptor, had a negative effect on the survival of the A431 tumor cell line, which contained large amounts of EGFR." (PMID 38201251, 2023). "These included well-known receptor tyrosine kinase genes (EGFR, TEK and OSMR) that activate MAPK and PI3K signaling pathways, and other tumor-promoter genes (ATP8B2, DAAM1, SLAMF8 and SRGN) as well as tumor-suppressor genes (A2M, DAPK1, RASSF8 and SOCS3)." (PMID 37190308, 2023). "Tumor samples from 155 patients with stages IIIB to IV NSCLC, who received EGFR-TKI therapy." (PMID 37152062, 2023). "Moreover, we also validated EGFR/ERK signaling changes between AnxA6 and AnxA6K299R-expressing tumor tissues from A431-xenograft nude mice." (PMID 37528485, 2023). "Here, we found that the TRPV1 is overexpressed by NANOG in cisplatin-resistant tumor cells and mediates Ca2+ influx and subsequent increases in autophagic EGF secretion, which activates the EGFR-AKT signaling pathway consequently contributing to cisplatin resistance." (PMID 37165076, 2023). "In addition, many well-characterized tumor-promoting proteins, including those with roles in metastasis, were increased on the cell surface, including c-MET, EGFR, VEGFR, ALK and ITGα5." (PMID 36674782, 2023). "In summary, the anti-EGFR iEDNs could deliver DOX and QDs simultaneously and efficiently to target tumor tissues." (PMID 36839675, 2023). "To enhance N-BPs tumor targeting, besides the nanoformulated ZA, we recently proposed a novel antibody-drug conjugate (ADC), made of ZA and the therapeutic anti-epithelial growth factor receptor (EGFR) antibody cetuximab (Cet)." (PMID 36765569, 2023). "It is worth mentioning that reprogramming TAMs can enhance the efficacy of EGFR-TKIs through a variety of mechanisms, including inhibition of TAM-related drug resistance pathway, reactivation of T cells in the TME, and reversal of EMT of tumor cells." (PMID 37649478, 2023). "In canine PAC, the activation of EGFR and HER2 has been reported in tumor tissue." (PMID 37798461, 2023).
tumor (continued). "Among the secondary objectives, it was possible to evaluate the impact of the oral EGFR/HER2 inhibitor on the signaling pathways of the receptors and downstream in the tumor tissue, as well as the correlations between the response and the inhibition of downstream signaling." (PMID 37190205, 2023). "Moreover, p38 MAPK activation enhanced epidermal growth factor receptor (EGFR) degradation and reduced tumor development." (PMID 36176197, 2023). "In addition, ERO1A, PKP2, and MERTK have been proved to promote the progress and drug resistance of NSCLC by enhancing the activation of tumor and PI3K, EGFR, and other signal pathways." (PMID 37101691, 2023). "Furthermore, according to these 7 key genes (ABCB1, CAP1, EGFR, ITGB1, MAPK1, PPARG, SNCA), we plotted the KM curves to show the survival state of high and low expression groups in tumor samples from the TCGA-PAAD dataset." (PMID 37857015, 2023). "This vector was administered in mice tumors where it achieved a high gene knock-out efficiency (the EGFR protein concentration in the tumor was decreased by 92%) and inhibited tumor growth more than vectors without CRISPR systems." (PMID 35939208, 2023). "We compared EGFR-amplified and non-amplified tumours in the primary and recurrent settings independently." (PMID 36765632, 2023). "Moreover, several articles have suggested tumor proliferation to take place during VRB treatment, with some suggesting a possible mechanism leading to epidermal growth factor receptor (EGFR) sensitization." (PMID 38137519, 2023). "Furthermore, the combination of gefitinib, an epidermal growth factor receptor inhibitor, and lenvatinib, an anti-tumour angiogenesis TKI, displayed potent anti-proliferative effects in epidermal growth factor receptor-expressing HCC cell lines in vitro." (PMID 36873490, 2023). "Impressively, the vaccinated animals showed a 76.4% reduction in tumor multiplicity 12 weeks after induction of the EGFR transgene compared with non-vaccinated controls." (PMID 37766136, 2023). "Epidermal growth factor receptor (EGFR) is overexpressed in up to 90% of PDAC and its upregulation may be related to more aggressive tumor behavior and a higher recurrence rate." (PMID 37304241, 2023). "At molecular level, activating mutations in epidermal growth factor receptor (EGFR) are the most frequent genetic mutation driving cancer cell proliferation and tumor malignancy in East Asians never-smoker NSCLC patients, especially in females." (PMID 37495186, 2023). "In addition, tumor-derived exosomes immunocaptured from HNSCC patients’ plasma have been found to contain high amounts of immunosuppressive and tumor growth-promoting mediators such as PD-L1, FasL, TGF-β and EGFR." (PMID 36817764, 2023). "The EGFR–COPA and NRG1–LGR4 pairs were expressed at higher levels in AC tumours than in MC tumours." (PMID 36690709, 2023). "Also, HER2 protein overexpressing tumours showed significantly higher expression of several receptor tyrosine kinases (RTKs) including FGFR4, EGFR, HER2 itself, as well as genes within the HER2 amplified region on Chr17q12-q21 (including GRB7)." (PMID 37740038, 2023). "Preclinical models have shown that EGFR, independent of its kinase activity, promotes tumor growth and causes drug resistance through activation of TKI-insensitive EGFR signaling." (PMID 37178919, 2023). "A hyaluronic acid-based niche scaffold with NK92 cell lines and human EGFR (epidermal growth factor receptor)-specific CAR-NK (chimeric antigen-receptor-modified Natural killer) cells were used to prevent relapse and metastases after tumor resection." (PMID 37349810, 2023). "Additionally, the activation of EGFR signaling can lead to the upregulation of COX-2, an enzyme involved in the production of prostaglandins that promote tumor growth, invasion, and angiogenesis." (PMID 37580790, 2023).
tumor (continued). "However, it is also possible to offer a doublet with anti-EGFR in the second-line setting if RAS wild-type and left-sided since data of resistance to anti-EGFR in MSI-H tumours is still scarce." (PMID 37377686, 2023). "In addition, the following pathway correlation analysis found that EGFR and ESR1 were positive correlated with tumor cell apoptosis, which further supported our conclusion." (PMID 37542141, 2023). "The EGFRvIII-DBTE exhibited specific binding activities and cytotoxicity against EGFRvIII-expressing GBM cells, while not binding to wild-type EGFR or inducing anti-tumor cytotoxicity in the absence of either targets, EGFRvIII or CD3." (PMID 36915911, 2023). "Clinical: CA 15.3, ACE, and CA-125 values.Pathological: ER, PR, HER2 expression, Ki-67 index, AR (AR: Androgen Receptor), EGFR, SBR grade, and cytokeratin (CK) 5/6 tumor expression.Radiomics: SUVmax at baseline and after the first cycle, in addition to the relative difference between them (ΔSUVmax)." (PMID 37958461, 2023). "In recurrent tumours, the EGFR pathway expression score for all patients, regardless of amplification status, was similar to that of the primary tumours with the EGFR amplification." (PMID 36765632, 2023). "We conducted a prospective observational study (WJOG13620L) of follow‐on next‐generation sequencing of circulating tumor DNA (ctDNA) in patients without driver alterations after EGFR testing." (PMID 37948122, 2023). "Cotreatment with afatinib and bevacizumab, an antiangiogenic monoclonal antibody, inhibited tumor growth in patients with EGFR-mutant NSCLC, without side effects." (PMID 37298389, 2023). "Very few coincident tumor suppressor alterations have been investigated in the context of oncogenic BRAF-driven autochthonous lung tumors, and the extent to which tumor suppressor effects differ in EGFR-driven tumors remains poorly understood 36,41–44." (PMID 37828026, 2023). "In fact, patients suitable for anti-EGFR, anti-VEGF, or immunotherapy only comprise of small portion of patients with CRC, whereas our results indicate significantly higher expression of HFG in most CRC tumor tissue than in normal tissue." (PMID 37496011, 2023). "All of these drugs are tyrosine kinase inhibitors (TKIs), except for austocystin D. TKIs target the epidermal growth factor receptor (EGFR) and Erb-B2 Receptor Tyrosine Kinase 2 (ERRB2) pathways, which are known to play crucial roles in tumor progression and metastasis." (PMID 37894479, 2023). "Here, an epidermal growth factor receptor (EGFR) CAR-T cell was engineered to express the chemokine receptor CCR6 and secrete PD1 blocking Single-chain antibody fragment (scFv) E27 to enhance their anti-tumor effects." (PMID 36982500, 2023). "Besides EGFR, PTPN23 promotes MVB sorting and lysosomal degradation of other oncogenic receptors, such as PDGFR and integrins, and elicits tumor suppressive activities by regulating cell adhesion, migration, and invasion." (PMID 37821451, 2023). "Similar results were obtained when analyses were performed in the population without known tumor EGFR/ALK alterations." (PMID 36928818, 2023). "The signaling plasticity offered by these SRC-dependent mechanisms may usurp and/or reinforce cell-autonomous pathways that drive tumor survival while bypassing other dependencies, including under the influence of BRAF/MEK or EGFR targeted therapies." (PMID 36759733, 2023). "Univariate analysis of sex or tumor location on dMMR/MSI, EGFR, and PD-L1 CPS in patients with CRC." (PMID 36802389, 2023). "Intra-tumor heterogeneity was higher in EAS EGFR-mutant-bearing never-smokers than in their EUR equivalents, On the other hand, EUR patients were characterized by more frequent mutations in other driver genes, among them KRAS." (PMID 36817482, 2023). "Tumor tissue from 49 patients with stage III or IV NSCLC who were without EGFR and ALK alterations were analyzed using targeted next-generation sequencing (NGS)." (PMID 37924135, 2023).